IL6 (interleukin 6)
Diseases named in the same sentence as IL6 in open-access papers (continued):
Sharing a sentence is not in itself a finding about the gene and the disease.
tumor (continued). "Notably, cytokines like IL-2, IL-6, TNF-α, and IFN-γ, known for their inflammatory enhancement properties, contribute to stimulating tumor cell immunity, thereby fostering anti-tumor activity." (PMID 39351237, 2024). "Additionally, IL-6, TNF-α, CXCL12, and leptin are considered to significantly promote tumor cell migration and proliferation, as well as inhibit apoptosis and activate autophagy, facilitating the development of tumor bone metastasis." (PMID 38571500, 2024). "ICIs exert their effects on the immune microenvironment surrounding tumors, and it has been demonstrated that CD8+ T lymphocytes, B cells, IL-6, and tertiary lymphoid structures (TLS) within tumor tissue all play a role in influencing the prognosis of ICI therapy for tumors." (PMID 39664382, 2024). "Conversely, TTI-101 did not affect tumor growth, metastasis, or plasma IL6 levels compared with vehicle control in orthotopic xenografts using T24 control cells." (PMID 38355560, 2024). "Some cell factors secreted by MON, such as interleukin-6, interleukin-10, and TGF-β, could inhibit lymphocyte activity and promote the growth of tumor cells." (PMID 38540104, 2024). "T helper (Th) cells play a crucial role in enhancing anti-tumor and anti-inflammatory immune responses by releasing various cytokines such as TNF-α, Granulocyte-Macrophage Colony-Stimulating Factor (GM-CSF), IL-2, IL-6, IL-10, IL-21, and others." (PMID 38755133, 2024). "Similarly, tumor cells defective in the RAS/KRAS pathway interact with immune cells in the TME by secreting a series of cytokines, such as TGF-β, IL-8, and IL-6, which are involved in macrophage reprogramming and the regulation of Treg differentiation." (PMID 38879686, 2024). "Only the specific inhibition of IL-6 trans-signaling, rather than total inhibition of IL-6 signaling, is sufficient to suppress tumor progression." (PMID 38890694, 2024). "In our study of IL-6 localization in OSCC tissues, we found that IL-6 expression was elevated in the stroma rather than in the tumor." (PMID 38510850, 2024). "In comparison with primary fibroblasts, metastatic fibroblasts express higher levels of soluble factors, including IL‐6, and CXCL12, suggesting the potential of metastatic fibroblasts to produce secreted factor to create a favourable microenvironment for tumour cell invasion." (PMID 38158643, 2024). "As beneficial functions, senescent cells promote senescence in neighboring cells by secreting IL-6 and IL-8, limiting tumor development in a cell non-autonomous manner." (PMID 38323313, 2024). "Il6 mRNA expression levels were not significantly different between Gsdmd-/- and WT mice in either tumor type." (PMID 39224600, 2024). "Moreover, the production of cytokines such as IL-2, IL-4, IL-6, IL-7, IFN-γ, IFN-α, TNF-α, CCL7, and CCL28 can stimulate an anti-tumor response." (PMID 38533507, 2024). "Increase the expression of NO, IL-1β, IL-6 and TNF-α in tumor-bearing mice." (PMID 39560523, 2024). "Interestingly, there was a significant correlation between TGF-β, IL-6, TLR-2 and TLR-4 in the primary CRC tumor and SPP1 expression by macrophages in the metastatic intrahepatic tumor." (PMID 39372792, 2024). "Additionally, in mouse models of xenograft with ovarian cancer cells, COL11A1 has been shown to stimulate IL-6 production via induction of TGF-β3, modulating the interaction between CAFs and tumor cells and amplifying tumor invasiveness and progression." (PMID 39769286, 2024). "In the tumor microenvironment, STAT3, which is predominantly activated by IL-10 and IL-21, but not by IL-6, enhances the effector function and survival of Texterm cells, thereby improving tumor regulation." (PMID 38582965, 2024). "Unlike IL-1, which has dual effects, IL-6 is a prototypical protumorigenic cytokine that promotes chronic inflammation while supporting tumor angiogenesis and inhibiting Th1 cell-mediated antitumor immunity." (PMID 39483474, 2024).
tumor (continued). "Also, MSC-derived IL-6 also activates neutrophils through the STAT3-ERK1/2 signal transduction pathway, and it shifts their immunosuppressive polarization towards tumour facilitation and supporting cancer progression." (PMID 39120301, 2024). "Specifically, in a study conducted on MDA-MB-231 BC cells, IL-6 protected malignant cells from chemotherapy-induced cytotoxicity and apoptosis via the involvement of the HIF-1, which regulates vital biological processes of tumour survival and progression." (PMID 39408212, 2024). "The tumor mass comprises several types of cells, such as tumor cells, macrophages, neutrophils, T-lymphocytes, fibroblasts, and endothelial cells that secrete a variety of mediators, including inflammatory cytokines such as TNF-α, IL-1, and IL-6." (PMID 38940936, 2024). "Our results showed a significant increase in levels of expression of inflammatory cytokine IL-1 β (p < 0.01), IL-6 (p < 0.001), TNF-α (p < 0.001), and other related genes including TRAF6 (p < 0.01), MYD88 (p < 0.01), and GDF-15 (p = 0.005) in tumor-bearing mice compared to controls." (PMID 39394174, 2024). "In addition, a significant positive correlation was noted between IL‐6 expression and the extent of tumour‐infiltrating macrophages in liver HCC, suggesting that macrophage infiltration and IL‐6 expression promote the progression of human HCC." (PMID 37974543, 2024). "Additionally, inflammation plays a role in this process, with inflammatory cytokines such as interleukin (IL)-6, IL-8, tumor necrosis factor (TNF) -α, and Prostaglandin (PGE) affecting the tumor microenvironment and potentially promoting tumor progression." (PMID 39050346, 2024). "CD109 influences key inflammatory pathways, including TGF-β/NF-κB, EGF/STAT3, and various inflammatory cytokines like IL-6 and IL-8, impacting inflammatory processes such as immune cell recruitment, macrophage polarization, immune microenvironment, EMT, and tumor progression." (PMID 39990858, 2024). "Interleukin-6 (IL-6) is a cytokine produced by a variety of cell types, including immune cells, non-fibroblasts, endothelial cells, and tumor cells." (PMID 38304429, 2024). "Additionally, IL-6 activates the STAT3 signaling cascade, leading to increased VEGF expression, which promotes tumor angiogenesis and growth." (PMID 37713112, 2024). "Furthermore, it was demonstrated that the concentrations of IL-6, IL-8, MCP-1, IP-10, MIP-1β, MIP-1α, TNF-α, GCSF, RANTES, IFN-γ, and VEGF are positively correlated with tumor size." (PMID 39596556, 2024). "IL-2 was detectable only in presence, but not in absence, of tumor cells, while TNFα was unchanged and all other cytokines (IL-6, IFN-γ, GM-CSF, IL-10) were slightly reduced without tumor cells." (PMID 38514793, 2024). "Moreover, the AKR1C1+ inflammatory fibroblast strongly expresses IL6 which interacts with IL6R expressed on DC1 and PRR-induced mo-DC, potentially contributing to tumor growth and therapeutic resistance." (PMID 38744958, 2024). "A variety of cells of the immune response release pro-inflammatory cytokines, including IL-1β, IL-1α, TNFα, IL-6, IL-12, IFN-γ, and chemokines such as CCL2 and CXCL12, which participate in the initiation, growth, and progression of tumor and development of drug resistance." (PMID 38571491, 2024). "However, the excised tumor tissues in the JQ1 group exhibited reduced protein levels of FAP‐α, α‐SMA, and IL6, as well as markedly decreased collagen deposition, as revealed by IHC, Masson's trichrome staining, Sirius Red staining, and IF assays." (PMID 38417121, 2024). "Similarly, interleukin 6 (IL6), also produced by CAFs, contributes to drug resistance mediating CXCR7 expression in tumor cells." (PMID 39195299, 2024). "Therefore, simultaneous blockade of IL6 and CCR2 appears to be a promising therapeutic approach for the treatment of HPV − tumors by augmenting the tumor-infiltrating NK cell population." (PMID 38468260, 2024).
tumor (continued). "We confirmed that the IL-6 signaling dependency did not rely on IL-6 trans-signaling, as blocking IL-6 trans-signaling in sgp130 hosts did not alter tumor growth compared to IL-6 trans-signaling-proficient WT hosts." (PMID 39128004, 2024). "It has been shown that blocking IL-6 enhances the therapeutic effect of immunotherapy by inducing and recruiting higher levels of CD4 + /CD8 + effector T cell production and recruitment in the tumor microenvironment." (PMID 38717677, 2024). "We found that in PDAC patients, but not in patients with oAC, high inflammatory biomarker (CRP and IL-6) serum levels at time of initial tumor diagnosis have a negative impact on OS." (PMID 38539528, 2024). "Furthermore, cytokines such as IL-6, IL-21, IL-17A, and tumor necrosis factor-α (TNF-α) induce tumor-supportive microenvironment, while interferon-γ (IFN-γ) exerts tumor-suppressive response." (PMID 38741166, 2024). "In vitro results suggest that this response occurs via a rapid membrane–mediated signaling pathway that increases tumor growth and activates PLC and PKC to increase the production of osteoclast activating proteins RANKL and IL-6 to inhibit the production of OPG." (PMID 38644978, 2024). "The tumor-immune cells microenvironment augments PD-L1 expression with pro-inflammatory cytokines, such as IFN-γ, tumor necrosis factor α (TNF-α), IL-10, interleukin-1 (IL-1) and interleukin-6 (IL-6)." (PMID 38384472, 2024). "Subsequently, the ELISA results of the tumor tissue demonstrated that the higher levels of TNF-α and IL-6 in hNVs, hNVs-EGCG and hNVs@Flu-EGCG groups and lower levels of IL-10 in hNVs, hNVs-EGCG and hNVs@Flu-EGCG groups compared to PBS and PLGA-Flu groups, showed the same result as before." (PMID 38637848, 2024). "Additionally, hypoxia activates HIF1α via the IL-6/STAT3 signaling pathway, resulting in increased CD133 expression and the maintenance of tumor cell stemness." (PMID 38230205, 2024). "The influx of mast cells into TME is mediated by tumor-cell-released chemoattractants, such as SCF or CCL15, and then mast cells can actively participate in the elimination of tumor cells through secreted histamin, TNF-α, and IL-1, IL-4 and IL-6." (PMID 38287290, 2024). "So, in the tumor microenvironment, the quantity of sIL-6R is smaller than the amount of sgp130 in BPH patients, resulting in the concomitant activation of two signaling pathways mediated by IL-6 (the classic way and trans-signaling)." (PMID 39452544, 2024). "Additionally, CD300E significantly enhances pathways such as TNF-α signaling, inflammatory response pathways, IL6-JAK signaling, and epithelial-mesenchymal transition (EMT), all of which are documented to potentially promote tumor growth and metastasis." (PMID 39144140, 2024). "GSEA highlighted that the high-risk group was characterized by enrichment in functions related to tumor progression, including epithelial-mesenchymal transition, hypoxia, the TNFA signaling pathway, inflammatory responses, collagen synthesis, and the IL6-JAK-STAT3 signaling pathway." (PMID 39136841, 2024). "Moreover, inflammatory markers, such as C-reactive protein (CRP), interleukin-6 (IL-6), and tumor necrosis factor-alpha (TNF-α), are elevated in CRC patients and correlated with tumor aggressiveness and poor prognosis." (PMID 38800241, 2024). "However, evidence is more limited for the role of IL6 and its cognate receptor, IL6R, within the tumour epithelium and microenvironment." (PMID 39766336, 2024). "RK improved T‐lymphopenia and decreased systemic IL‐6 concentrations, resulting in alleviation of cachexia and increased survival of cachexigenic tumour‐bearing mice, even under chemotherapy and independent of COX inhibition." (PMID 38302863, 2024). "Nevertheless, tumor cell-derived IL-6 and PTHrP may have a significant impact on cancer cachexia through the activation of BAT and/or adipose tissue browning, particularly in animal tumor models." (PMID 38334644, 2024).
tumor (continued). "TMQ administration downregulated the tumor necrosis factor-α (TNF-α), interleukin-6 (IL-6), and the glutathione (GSH) level and upregulated interferon-γ (IFN-γ), reactive oxygen species (ROS), and malondialdehyde (MDA) levels in the serum of tumor mice." (PMID 39508039, 2024). "In contrast, trametinib inhibited IL-6-induced AP-1/JUNB but not MYC transactivation activity in these tumor cells." (PMID 39160158, 2024). "For example, TG2 mediates NF-κB activation, interleukin-6 (IL-6) upregulation, and Janus kinase/ signal transducer and activator of transcription 3 (JAK/STAT3) induction, thus promoting tumor progression, the acquisition of a stem-like phenotype, and neratinib resistance." (PMID 38474044, 2024). "Silencing of SOCS1 allowed IL-6 to induce CD155 overexpression; thus, constitutive expression of SOCS1 in tumor cells prevented CD155 overexpression upon IL-6 stimulation and may account for the weak correlation found in tumors." (PMID 39596207, 2024). "In this regard, Ohlund and his colleagues reported that CAFs with a low expression level of the α-SMA marker produce a large amount of IL-6, and CAFs that express a high amount of FAP and α-SMA produce more TGF-β that both subtypes play an important role in tumor progression." (PMID 39030445, 2024). "It is clear from these findings that the mechanism by which CAFs secrete IL-6 to induce EMT in tumor development might enhance tumor incidence and spread as well as tumor medication resistance." (PMID 38244071, 2024). "As a critical regulator of the GP130/IL-6/STAT3 pathway, CD109 may act as a crucial link between chronic inflammation and tumor development." (PMID 39990858, 2024). "IL-10 and IL-21, but not IL-6, activate STAT3, promote tumor-specific Texterm cell-associated gene expression, and suppress TexProg cell-related gene expression, resulting in the development and enhanced effector functions of Texint cells in tumors." (PMID 38582965, 2024). "FOSL1 triggers the activation of the IL-6/JAK/Stat3 signaling pathway, resulting in a malignant switch in breast tumor cells that leads to increased release of pro-angiogenic factors such as MMP-9, VEGF, and TGF-β from the tumor cells." (PMID 38791400, 2024). "Indeed, the tumour presented a massive overexpression of pro-inflammatory cytokines, comprising TNFA, IFN-γ, IL6-Jak-STAT3, and IL2-STAT5 signalling cascade." (PMID 39421445, 2024). "Furthermore, IL-6 can influence other cells within the TME to create a favorable growing environment for tumor cells, allowing for easier angiogenesis and tumor escape from immune surveillance." (PMID 38890642, 2024). "On the other hand, TAMs can also activate the epithelial mesenchymal transition (EMT) in tumors through chemokines and cytokines, such as TGF-β, IL-10, IL-6, matrix metalloproteinases (MMPs), and vascular endothelial growth factor (VEGF), to promote tumor invasion and migration." (PMID 38424624, 2024). "Moreover, the increment in IL-6 levels subsequently enhanced the migratory potential and EMT of CRC tumor cells." (PMID 38612842, 2024). "IL-6-induced tumor neovascularization and vascular remodeling not only facilitate cancer metastasis, but also significantly modulate the endocrine function of IL-6 by regulating vascular transport." (PMID 38482486, 2024).
tumor (continued). "According to research, metformin may selectively target cancer stem cells (CSCs) over non-stem cancer cells (NSCCs), as it inhibits inflammatory pathways such as NF-κB and IL6 in CSCs, resulting in selective CSC death and tumor growth reduction." (PMID 39201332, 2024). "In addition, LAs reduce inflammatory cytokines (e.g., IL-6, TNF-α) and adhesion molecules, preserving NK cell function and promoting lymphocyte proliferation, which enhances anti-tumor immune responses." (PMID 39766169, 2024). "Notably, expression of interleukin 6 (IL6), a potent growth factor for PCs, was upregulated, suggesting autocrine regulation of EMM tumor growth." (PMID 38493239, 2024). "Notably, complete tumor regression and good drug tolerance were observed in 80−100% of treated mice, and significant increases in IFN‐β, IL‐6, and TNF‐α were observed in the tumor and plasma." (PMID 38525112, 2024). "The TAM model in the simulated tumor microenvironment was treated with dCP1 and dCPP, respectively, and it was found that glycopeptide can better reduce Mrc1 in M2-like TAM and increase the relative expression levels of IL-1β and IL-6 mRNA." (PMID 38743074, 2024). "Several factors in the PDAC microenvironment contribute to impaired DC function: tumor-derived TGF-β, IL-10, and IL-6 suppress DC survival and proliferation, MDSCs inhibit DC maturation, and a subset of immunosuppressive CD11b+ DCs can induce Treg generation and cytotoxic T cell (CTL) suppression." (PMID 39178856, 2024). "Tumor homogenates were thoroughly washed to make sure that they did not contain any IL-6-inducing activity." (PMID 39518029, 2024). "Once Tregs reach the tumor, differentiation/polarization and activation is induced by a variety of tumor- and immune-derived factors, including TGFβ, IL-10, PGE2/COX2, IL-35, adenosine, IL-6/STAT3, and even has_circ_0069313, a tumor-derived circular RNA that helps Tregs maintain FoxP3 levels." (PMID 38254801, 2024). "To clarify the mechanism of ‘the impact of IL-6 on TAMs, we performed GSVA analysis on single-cell data and found that the downstream JAK/STAT3 pathway of IL-6 was significantly activated and further increased with tumor progression." (PMID 38424624, 2024). "It is known that IL-6 is a major pro-inflammatory cytokine with a broad spectrum of negative impacts on tumor cells, contributing to tumor malignancy." (PMID 38612842, 2024). "In turn, tumor-educated Gr1+CD11b+ (Tu-Gr1+CD11b+) cells rapidly and transiently converted low metastatic SCA1– cells into highly metastatic SCA1+ cells via secreted oncostatin M (OSM) and IL-6." (PMID 38236642, 2024). "In addition, there was a significantly increased secretion of IL-6, IL-10, VEGF, and MCP-1, which promote tumor progression." (PMID 38473285, 2024). "Increasing research indicates that adipokines (such as leptin, resistin, visfatin, etc.)and inflammatory factors (such as IL-1β, IL-6, chemokines, FABP4, etc.)secreted by BMA can also regulate angiogenesis, indirectly facilitating the progression of tumor bone metastasis." (PMID 38571500, 2024). "Studies showed that activation of YAP is an important step in TAM recruitment towards TME in HCC via modulating the levels of IL-6, CSF-1 and CCL-2 secreted by the tumour cells, thereby inducing the formation of tumour initiation cells and remodelling the composition of TME." (PMID 39320855, 2024). "Additionally, the increase in cytokines such as IL-6 and HGF emphasizes their role in surgery-induced tumor growth and metastasis and the role of other cytokines like MCP-2 in immunosuppression." (PMID 39451257, 2024). "To identify factors that correlate with IL-6, we performed the linear regression analyses in the non-tumor group and the tumor group and observed that Vpr concentration was the single molecule that correlated with IL-6 in the non-tumor group." (PMID 38166062, 2024).